COL3A1 (collagen type III alpha 1 chain)
Description:
Collagen type III occurs in most soft connective tissues along with type I collagen. Involved in regulation of cortical development. Is the major ligand of ADGRG1 in the developing brain and binding to ADGRG1 inhibits neuronal migration and activates the RhoA pathway by coupling ADGRG1 to GNA13 and possibly GNA12.
Synonyms: EDS4A; EDSVASC; PMGEDSV
Tractability: Antibody: its Gene Ontology location is reachable by antibodies, with high confidence; UniProt places it where antibodies can reach, with medium confidence; UniProt predicts a signal peptide or a membrane-spanning region. PROTAC: ubiquitination databases record sites on it. Other modalities: an approved drug acts on it.
Gene: Protein-coding gene on chromosome 2 (188,974,371 to 189,012,746, forward strand). Ensembl gene ENSG00000168542.
Subcellular location: Secreted, extracellular space, extracellular matrix
Subcellular location (Human Protein Atlas): Endoplasmic reticulum; Predicted to be secreted
Pathways (Reactome):
Extracellular matrix organization: Assembly of collagen fibrils and other multimeric structures; Collagen biosynthesis and modifying enzymes; Collagen chain trimerization; Collagen degradation; ECM proteoglycans; Fibronectin matrix formation; Integrin cell surface interactions; Non-integrin membrane-ECM interactions; Syndecan interactions
Developmental Biology: Developmental Lineage of Pancreatic Ductal Cells; NCAM1 interactions
Signal Transduction: MET activates PTK2 signaling; Signaling by PDGF
Immune System: Immunoregulatory interactions between a Lymphoid and a non-Lymphoid cell
Vesicle-mediated transport: Scavenging by Class A Receptors
Gene Ontology:
Molecular function: extracellular matrix structural constituent; extracellular matrix structural constituent conferring tensile strength; integrin binding; platelet-derived growth factor binding; protease binding; protein binding; SMAD binding
Biological process: cell-matrix adhesion; collagen fibril organization; heart development; integrin-mediated signaling pathway; negative regulation of immune response; peptide cross-linking; response to cytokine; response to radiation; skin development; supramolecular fiber organization; transforming growth factor beta receptor signaling pathway; wound healing; cerebral cortex development; negative regulation of neuron migration; platelet activation; positive regulation of Rho protein signal transduction; skeletal system morphogenesis; animal organ development; aorta development; aorta smooth muscle tissue morphogenesis; basement membrane organization; cartilage development; chondrocyte differentiation; elastic fiber assembly; endochondral bone morphogenesis; and 14 more
Cellular component: collagen type III trimer; extracellular matrix; extracellular region; endoplasmic reticulum lumen; collagen trimer; fibrillar collagen trimer
Genetic constraint (gnomAD): Loss-of-function variants: 41 observed, 182.89 expected, observed/expected ratio (o/e) 0.22, 90% interval 0.17 to 0.29. The upper end of that interval is the gene's LOEUF score, 0.29, which puts it in group 1 of 6, group 1 being the genes least tolerant of losing a copy. Missense variants: 1,322 observed, 1,868 expected, observed/expected ratio (o/e) 0.71, 90% interval 0.68 to 0.74. Synonymous variants: 632 observed, 623.51 expected, observed/expected ratio (o/e) 1.01, 90% interval 0.95 to 1.08.
Gene-disease validity (ClinGen):
ClinGen rates the evidence that COL3A1 causes each of these diseases.
Ehlers-Danlos syndrome, vascular type (autosomal dominant): Definitive.
Homologues: Orthologues: chimpanzee COL3A1 (99% identical), macaque COL3A1 (98% identical), dog COL3A1 (93% identical), rabbit COL3A1 (93% identical), pig COL3A1 (93% identical), mouse Col3a1 (91% identical), rat Col3a1 (91% identical), guinea pig COL3A1 (90% identical), tropical clawed frog col3a1 (74% identical). Paralogues in human: COL1A1 (62% identical), COL2A1 (62% identical), COL5A2 (55% identical), COL1A2 (53% identical), COL11A1 (42% identical), COL5A1 (42% identical), COL11A2 (41% identical), COL5A3 (38% identical), COL4A1 (37% identical), COL4A5 (36% identical), COL4A3 (34% identical), COL4A4 (34% identical), and 25 more.
Diseases named in the same sentence as COL3A1 in open-access papers:
COL3A1 is named in the same sentence as 298 diseases in open-access papers, as found by Europe PMC text mining. Sharing a sentence is not in itself a finding about the gene and the disease. The quoted sentences say what the papers report.
vascular Ehlers-Danlos syndrome (75 papers, 2006 to 2026). "Among the 13 currently recognized subtypes, vascular EDS (vEDS) is one of the most severe and is caused by heterozygous pathogenic variants in the COL3A1 gene, located on chromosome 2q32.2." (PMID 40981013, 2025). "Mutations in the COL3A1 gene result in Ehlers-Danlos syndrome type IV and alterations in the size and distribution of the major collagen fibrils of the dermis." (PMID 40332597, 2025). "Vascular Ehlers-Danlos Syndrome (vEDS), caused by mutations in the COL3A1 gene, is characterised by connective tissue fragility, particularly within the vascular system." (PMID 41245867, 2025). "Vascular EDS (COL3A1 mutations) was rare but strongly associated with spontaneous rupture events, with an odds ratio of 7.5 (95% CI 4.2–13.2, P < 0.001)." (PMID 40110250, 2025). "Vascular EDS (vEDS), a subtype of this condition, is caused by mutations in the COL3A1 gene, which encodes type III collagen, an essential component of blood vessel walls." (PMID 39931243, 2025). "Vascular Ehlers-Danlos syndrome, resulting from mutations in the COL3A1 gene, and Loeys-Dietz syndrome, linked to TGFBR1 and TGFBR2 mutations, are known to predispose individuals to arterial dissections due to connective tissue fragility." (PMID 41362507, 2025). "Among these subtypes, vascular EDS (vEDS), an autosomal dominant disorder, is linked to mutations in the COL3A1 and/or COL1A1 genes, which encode for type III and type I collagen, respectively." (PMID 41020269, 2025). "Since the presence of PVs in the COL3A1 gene are associated with vascular Ehlers-Danlos syndrome (OMIM#130050), its presence in heterozygosis would support diagnosis of this disorder and the causality of symptoms." (PMID 41466732, 2025). "Of these, vascular EDS (vEDS) has an autosomal dominant inheritance pattern and is associated with mutations in the COL3A1 and/or COL1A1 genes, which encode type III and type I collagens, respectively." (PMID 38485809, 2024). "The type III collagen gene (COL3A1), the causative gene of vascular EDS, is distributed in many important organs that require stretching, including the heart, blood vessels, gastrointestinal tract, and uterus." (PMID 39177919, 2024). "Vascular Ehlers-Danlos syndrome (vEDS) is a rare connective tissue disorder with a high risk for arterial, bowel, and uterine rupture, caused by heterozygous pathogenic variants in COL3A1." (PMID 38623759, 2024). "Vascular EDS (vEDS) is an inherited connective tissue disorder caused by pathogenic variants in the COL3A1 gene." (PMID 36977837, 2023). "For example, a patient presenting with SCAD who is found to have a pathogenic variant in COL3A1 should undergo a comprehensive evaluation for any additional signs and symptoms associated with vascular Ehlers-Danlos syndrome." (PMID 37979122, 2023). "Vascular EDS (vEDS) is caused by heterozygous pathogenic variants in COL3A1, which result in defective or reduced secretion of collagen III by skin fibroblasts." (PMID 36751332, 2023). "Vascular Ehlers-Danlos syndrome (vEDS) is rare connective tissue disorder caused by pathogenic variants in the COL3A1 gene." (PMID 36977837, 2023). "Vascular Ehlers Danlos syndrome (vEDS) is a multisystemic disorder inherited as an autosomal dominant trait caused by a pathogenic variant in the COL3A1 gene." (PMID 36832261, 2023). "Herein, we report the successful treatment of the repeated intestinal perforations in a case of vascular EDS with a novel COL3A1 mutation via multiple surgical interventions." (PMID 37171638, 2023). "Primary spontaneous pneumothorax (PSP) is a manifestation of Vascular Ehlers-Danlos syndrome (vEDS) caused by heterozygous mutations in the COL3A1 gene." (PMID 37800821, 2023). "There were also two patients with variants in the COL3A1 gene where known pathogenic variants are autosomal dominant and causal for Ehlers Danlos syndrome type IV and rare type III." (PMID 35918752, 2022).
vascular Ehlers-Danlos syndrome (continued). "The first mutation of COL3A1 was described in an inherited Ehlers-Danlos syndrome type IV patient in 1988." (PMID 35754816, 2022). "Vascular EDS, a rare inherited autosomal-dominant disorder caused by COL3A1 pathogenic variants, is characterized by a high frequency of de novo variants." (PMID 34946877, 2021). "Similar, but clinically different is the COL3A1 mutation caused Vascular Ehlers-Danlos syndrome (vEDS) (previously known as type IV)." (PMID 35052389, 2021). "Heterozygous mutation of COL3A1 on chromosome 2q32 can cause vascular Ehlers-Danlos syndrome (EDS-VASC)." (PMID 33083483, 2020). "The absence of classical UPR activation was also previously observed in other connective tissue disorders, such as in OI patients with mutations in COL1A1 disrupting triple helix formation and in vascular EDS patients carrying COL3A1 mutations." (PMID 31288483, 2019). "Bruising is common with COL3A1 missense variants, but massive hemorrhage is rare except with viscus rupture with vascular EDS, despite the two hemostasis domains found in collagen III." (PMID 28704418, 2017). "Disease-causing COL3A1 variants result predominantly in vascular Ehlers-Danlos syndrome (EDS type IV) (MIM 130050)." (PMID 28704418, 2017). "The genetic study identified the COL3A1 gene mutation; accordingly, the patient was diagnosed with the Ehlers-Danlos syndrome type IV (vascular type)." (PMID 27293936, 2016). "One exception is seen in patients and animal models of Ehlers-Danlos syndrome type IV in which the COL3A1 gene mutation results in reduced collagen III but with concurrent increased myofibroblast expression." (PMID 25789326, 2015). "Vascular EDS (formerly EDS type IV) is an autosomal dominant disorder of type III collagen caused by mutations in COL3A1 and occurs in 1 in 100,000 to 1 in 200,000 patients." (PMID 23401778, 2013). "If the clinical features are suggestive of vascular EDS, then the analysis of COL3A1 can detect a mutation in 98-99% of cases." (PMID 23401778, 2013). "A single family considered affected by EDS-HT was found with a mutation in the COL3A1 gene, which, in turn, is typically mutated in the vascular EDS." (PMID 23227356, 2012). "Conversely, >95% of the cases of vascular EDS are due to mutations in the gene encoding collagen type III (COL3A1), which is markedly expressed in vessels." (PMID 23227356, 2012). "Ehlers-Danlos syndrome type IV, the vascular type, is a rare disorder caused by mutations in the COL3A1 gene on chromosome 2q31." (PMID 21699676, 2011). "An underlying collagen vascular disorder was suspected, and genetic testing revealed a mutation in the collagen type III, α1 (COL3A1) gene, which is consistent with a diagnosis of Ehlers-Danlos syndrome type IV." (PMID 21699676, 2011). "Similarly, mutations in other extracellular matrix genes, such as COL3A1 in vascular EDS, can lead to vascular fragility and rupture." (PMID 40110250, 2025). "For example, our findings suggest that patients with COL3A1-associated vascular EDS may benefit from beta-blockers to reduce arterial stress." (PMID 40110250, 2025). "While Vascular Ehlers-Danlos Syndrome (vEDS) is primarily linked to mutations in COL3A1, there is some phenotypic overlap with LDS, particularly concerning vascular fragility, prompting research into potential roles of TGFBR2 mutations in vEDS-like presentations." (PMID 40612107, 2025). "The identified missense mutation in the COL3A1 gene (c.2095G>T, p.Gly699Cys) might be a novel pathogenic variation causing vascular Ehlers-Danlos syndrome." (PMID 37171638, 2023). "More than 500 mutations in COL3A1 have been reported to cause vascular EDS (OMIM # 130050)." (PMID 37894834, 2023). "Vascular EDS patients with pathogenic variants in COL3A1, have structural defects of the C-propeptide chain of collagen type III, defects that are characterized by decreased thermal stability and abnormalities in proteolytic processing that can produce procollagen suicide." (PMID 36756177, 2023).
vascular Ehlers-Danlos syndrome (continued). "In this cohort, rare variants with evidence of pathogenicity were also identified in COL3A1 (associated with Vascular Ehlers-Danlos syndrome), LOX (familial thoracic aortic aneurysm and dissection), and FLNA (disorders associated with neuronal migration abnormalities) [21•]." (PMID 37979122, 2023). "The missense COL3A1 mutation (c.2095G>T, p.Gly699Cys) found in this case might be a novel pathogenic variation causing vascular EDS." (PMID 37171638, 2023). "As described in our previous work, it is worth noting that pEDS1 also carried a frameshift variant in COL3A1 and thus might be affected by vascular EDS (vEDS)." (PMID 35571048, 2022). "Vascular Ehlers-Danlos syndrome (vEDS) is a rare autosomal dominant hereditary collagen disease caused by a defect or deficiency in the pro-α1 chain of type III procollagen encoded by the COL3A1 gene." (PMID 32471395, 2020). "Type 4 EDS (also known as vascular EDS) occurs due to mutations in type 3 collagen (COL3A1 gene)." (PMID 32562158, 2020). "However, the examination identified the COL3A1 gene mutation, and so the Ehlers-Danlos syndrome type IV (vascular type) was diagnosed." (PMID 27293936, 2016). "Vascular Ehlers-Danlos syndrome (vEDS) is a genetic disease caused by a pathogenic mutation in the COL3A1 gene." (PMID 37404745, 2023). "Vascular Ehlers-Danlos syndrome (vEDS) is a rare inherited connective tissue disorder due to pathogenic variants in COL3A1 leading to medium-size-artery (MSA) dissection, aneurysm, rupture." (PMID 36262204, 2022). "Such an instability could well contribute to the disease mechanism in human patients and has been reported to be involved for mutations in COL2A1 causing Kniest dysplasia, in COL3A1 causing Ehlers-Danlos syndrome type IV and in COL17A1 causing junctional epidermolysis bullosa." (PMID 29439465, 2018). "Vascular Ehlers-Danlos syndrome (vEDS) is a dominantly inherited connective tissue disorder caused by mutations in the COL3A1 gene that encodes type III collagen (COLLIII), which is the major expressed collagen in blood vessels and hollow organs." (PMID 29346445, 2018). "Aortic dissection or rupture is a leading cause of mortality in vascular Ehlers-Danlos syndrome (VEDS), a disorder caused by mutations in the COL3A1 gene." (PMID 42048161, 2026). "Aortic dissection or rupture is a major cause of mortality in vascular Ehlers-Danlos syndrome (vEDS), a connective tissue disorder caused by heterozygous mutations in the collagen type III alpha 1 chain (COL3A1) gene." (PMID 39836470, 2025). "The diagnosis of vascular Ehlers-Danlos syndrome (COL3A1), was made in a proband and two of the six tested relatives." (PMID 38740897, 2024). "Other syndromic disorders include Loeys-Dietz syndrome (LDS) and vascular Ehlers-Danlos syndrome (vEDS) which are caused by mutations in the TGF-β signaling cascade and in COL3A1, respectively." (PMID 33195187, 2020). "Vascular Ehlers-Danlos syndrome (vEDS, OMIM#130050) is a rare autosomal dominant inherited connective tissue disorder caused by mutations in the COL3A1 gene encoding the pro-α 1 chain of type III procollagen (COLLIII)." (PMID 29346445, 2018). "Forty-five years later, we still recognize arterial rupture as the hallmark of vascular EDS (EDS IV) with intestinal and organ perforation which we regard as specific feature to this subtype caused by a COL3A1 gene mutation." (PMID 23762718, 2013). "Vascular Ehlers Danlos Syndrome (vEDS) is a connective tissue disorder caused by COL3A1 mutations for which there are no treatments due to a limited understanding of underlying mechanisms." (PMID 40280907, 2025). "Vascular Ehlers-Danlos syndrome (vEDS) is an autosomal dominant condition known to cause multiple aneurysms and arterial dissection at a young age owing to a mutation in the gene for type III collagen, COL3A1." (PMID 35155630, 2022). "Vascular EDS is a rare and severe CTD mainly due to variants in the COL3A1 gene." (PMID 36262204, 2022).
vascular Ehlers-Danlos syndrome (continued). "Col3a1+/G182R mice showed a spontaneous mortality caused by thoracic aortic rupture that recapitulates the vascular Ehlers-Danlos syndrome with a lower survival rate in males, thin non-inflammatory arteries and an altered arterial collagen." (PMID 35245290, 2022). "Ehlers-Danlos syndrome type IV, also known as vascular Ehlers-Danlos syndrome, is an inherited condition associated with abnormal procollagen III synthesis resulting from heterozygote mutations in the COL3A1 gene." (PMID 34946804, 2021). "Neither case (BPt00521469 and ScPt0162409J) with COL3A1 variants has typical characteristics of vascular Ehlers-Danlos syndrome." (PMID 33125268, 2020). "Bi-allelic mutations in COL3A1, encoding type III (pro) collagen, cause cobblestone-like cortical malformation and white matter changes, but these are not observed in vascular EDS caused by heterozygous COL3A1 mutations." (PMID 30535813, 2019). "However, neither the patient nor his mother or other individuals on the maternal side of the family have clinical symptoms suggestive of vascular Ehlers-Danlos syndrome (EDS type IV), the only syndrome known to be caused by pathogenic mutations in COL3A1." (PMID 27964749, 2016). "Surprisingly, two out of the three patients with a COL3A1 mutation did not present skin or facial features reminiscent of vascular Ehlers-Danlos Syndrome (vEDS)." (PMID 25644172, 2015). "COL1A2, COL3A1, COL5A2 are a group of collagen genes in which mutations are associated with several connective diseases such as the involvement of COL3A1 mutations in intracranial aneurysms and Ehlers-Danlos syndrome type IV with aortic and arterial aneurysms." (PMID 24079748, 2013). "Vascular Ehlers-Danlos syndrome (vEDS, OMIM #130050) is a rare autosomal dominant inherited condition caused by genetic defects in the COL3A1 gene coding for collagen III (OMIM *120180)." (PMID 35245290, 2022). "Importantly, several heterozygous variants causing Glutamic acid>Lysine changes in COL3A1 have been reported to cause clinical features of classical EDS with a hyperextensible skin and skin fragility but also generalised tissue fragility as seen in vascular EDS." (PMID 39629459, 2024).